CEP295NL (CEP295 N-terminal like)
Synonyms: KIAA1731NL; DDC8
Tractability: No criterion of Open Targets' tractability assessment is met for any kind of drug.
Gene: Protein-coding gene on chromosome 17 (78,890,579 to 78,903,217, reverse strand). Ensembl gene ENSG00000178404.
Subcellular location: Cell projection, cilium
Subcellular location (Human Protein Atlas): Vesicles
Gene Ontology:
Biological process: regulation of centriole replication
Cellular component: centriole; centrosome; cytosol; cilium
Genetic constraint (gnomAD): Loss-of-function variants: 6 observed, 6.48 expected, observed/expected ratio (o/e) 0.93, 90% interval 0.5 to 1.71. That is too few expected variants to judge how well the gene tolerates losing a copy. Missense variants: 709 observed, 770.32 expected, observed/expected ratio (o/e) 0.92, 90% interval 0.87 to 0.98. Synonymous variants: 294 observed, 311.6 expected, observed/expected ratio (o/e) 0.94, 90% interval 0.86 to 1.04.
Homologues: Orthologues: chimpanzee CEP295NL (99% identical), rat Timp2 (37% identical), mouse Cep295nl (36% identical), zebrafish alms1 (5% identical). Paralogues in human: CEP295 (27% identical), ALMS1 (14% identical), C10orf90 (3% identical).
Diseases named in the same sentence as CEP295NL in open-access papers:
CEP295NL is named in the same sentence as 1 disease in open-access papers, as found by Europe PMC text mining. Sharing a sentence is not in itself a finding about the gene and the disease. The quoted sentences say what the papers report.
diabetic neuropathy (1 paper, 2025). A chronic, pathological complication associated with diabetes mellitus, where nerve damages are incurred due to diabetic microvascular injury involving small blood vessels that supply these nerves, resulting in peripheral and/or autonomic nerve dysfunction. "In addition, further research is needed to explore the roles of specific biomolecules implicated in diabetic neuropathy development, such as SLC30A1, TRBJ2‐7, OLFM1, TCF7L2, MCF2L, CEP295NL, CEACAM22P, TSHZ2, and PDZD4." (PMID 40692573, 2025).